ZNF14 (zinc finger protein 14)
Description:
May be involved in transcriptional regulation.
Synonyms: GIOT-4; KOX6
Tractability: PROTAC: ubiquitination databases record sites on it.
Gene: Protein-coding gene on chromosome 19 (19,710,472 to 19,733,112, reverse strand). Ensembl gene ENSG00000105708.
Subcellular location: Nucleus
Subcellular location (Human Protein Atlas): Cytosol; Nucleoplasm
Pathways (Reactome):
Gene expression (Transcription): Generic Transcription Pathway
Gene Ontology:
Molecular function: DNA-binding transcription factor activity, RNA polymerase II-specific; RNA polymerase II transcription regulatory region sequence-specific DNA binding
Biological process: regulation of transcription by RNA polymerase II; regulation of DNA-templated transcription
Cellular component: nucleus
Genetic constraint (gnomAD): Loss-of-function variants: 9 observed, 12.07 expected, observed/expected ratio (o/e) 0.75, 90% interval 0.45 to 1.3. The upper end of that interval is the gene's LOEUF score, 1.3, which puts it in group 5 of 6, group 1 being the genes least tolerant of losing a copy. Missense variants: 711 observed, 801.41 expected, observed/expected ratio (o/e) 0.89, 90% interval 0.83 to 0.94. Synonymous variants: 239 observed, 257.77 expected, observed/expected ratio (o/e) 0.93, 90% interval 0.83 to 1.03.
Homologues: Orthologues: chimpanzee ZNF14 (90% identical), macaque ZNF14 (88% identical), dog ZNF791 (52% identical). Paralogues in human: ZNF709 (61% identical), ZNF791 (52% identical), ZNF433 (50% identical), ZNF44 (50% identical), ZNF700 (50% identical), ZNF443 (50% identical), ZNF441 (49% identical), ZNF823 (49% identical), ZNF799 (49% identical), ZNF442 (46% identical), ZNF878 (46% identical), ZNF563 (37% identical), and 3 more.
Diseases named in the same sentence as ZNF14 in open-access papers:
ZNF14 is named in the same sentence as 8 diseases in open-access papers, as found by Europe PMC text mining. Sharing a sentence is not in itself a finding about the gene and the disease. The quoted sentences say what the papers report.
liver fibrosis (1 paper, 2022). "On the purpose of exploring the clinical association of TFs, we identified inflammation-, fibrosis- and survival associated TFs, with ZNF14 were predictive of advanced liver fibrosis and poor survival." (PMID 36440333, 2022). "Activated TFs ZNF14 and ZNF512 were positively correlated with advanced liver fibrosis." (PMID 36440333, 2022).
lung diseases (1 paper, 2022). "However, studies on RBM11 and ZNF14 in lung diseases are rare." (PMID 36523766, 2022).
oropharyngeal cancer (1 paper, 2015). Carcinoma, predominantly squamous cell, arising from the epithelial cells of the oropharynx. "All but ZNF14 are located on the 19q13 locus, which was shown to be epigenetically silenced in oropharyngeal cancer, supporting the hypothesis that ZNF160, ZNF420, ZNF585B, and ZNF71 are epigenetically regulated in a coordinated fashion." (PMID 26544568, 2015).
psoriasis (1 paper, 2025). An autoimmune condition characterized by red, well-delineated plaques with silvery scales that are usually on the extensor surfaces and scalp. "In the CD group, the AUC of diagnostic genes H2BC5 and AQP9 were 61.333% and 93.909%, in the psoriasis group, the AUC of IL1R2, AQP9, ZNF14 and H2BC5 were 75.641%, 82.906%, 93.162%, and 51.709%." (PMID 40093802, 2025). "The same ROC analysis was also performed in the psoriasis group, and the AUC of IL1R2, AQP9, ZNF14 and H2BC5 were obtained to be 78.728%, 78.698%, 92.194% and 80.562%." (PMID 40093802, 2025).
tumor (1 paper, 2015). "Of all remaining five ZNF protein genes, ZNF14, ZNF160, ZNF71, ZNF420 and ZNF585B, DNA methylation was significantly higher in tumor samples, as compared to normal controls." (PMID 26544568, 2015). "Twenty candidate genes (84%) showed methylation in greater than 50% of primary tumor, including ADFP, FUZ, ZNF71, ENPP5, ZNF211, and ZNF14." (PMID 26544568, 2015). "Furthermore, DNA methylation changes in selected ZNF genes (ZNF14, ZNF 160, and ZNF420) are detectable in both tumor and saliva of HNSCC patients with high specificity and represent promising biomarkers for the development of non-invasive assays for the detection and surveillance of HNSCC." (PMID 26544568, 2015).
ZNF14 also shares sentences with these, for which no sentence is quoted: Alzheimer disease (1 paper); cancer (1); Tics (1).